CD4 (CD4 molecule)
Diseases named in the same sentence as CD4 in open-access papers (continued):
Sharing a sentence is not in itself a finding about the gene and the disease.
colitis (continued). "Previous studies have described an important role for CD4+ T cells in the maintenance of gut homeostasis, and the dysregulation of gut CD4+ T cell responses have been shown to exacerbate colitis severity." (PMID 36704549, 2022). "This suggests, further, that the contribution of unopposed STAT3α to TNBS-induced colitis in CD4+ cells supersedes its effects in myeloid and epithelial cells." (PMID 36498596, 2022). "Although both CD45RBlow and CD45RBhighCD4+ T cells homed to the intraepithelial and lamina propria compartments of both the small and large intestine, CD45RBlow or total unfractionated CD4+ T-cells were incapable of inducing colitis." (PMID 36012618, 2022). "In contrast, CD69+CD103+ CD4+ TRM cells only accounted for 2.2% of IFNγ- and 5.1% of IL-17A–expressing CD4+ T cells in control mice, 6.5% of IFNγ- and 3.9% of IL-17A–expressing CD4+ T cells in DSS-induced colitis, respectively." (PMID 35844584, 2022). "Meanwhile, the correlation analysis showed that Alistipes was negatively correlated with MPO and CD4+CD45+CCR7+ and CD4+CD45+CCR7+ cells when experimental colitis was treated with COG." (PMID 35832382, 2022). "It will be interesting to evaluate the active status of CD4+ T cells to determine impact of UroA on T cell active status in colitis." (PMID 36159798, 2022). "We next analyzed TIGIT expression among subsets of CD4+ T cells from DSS-induced colitis by flow cytometry." (PMID 35844584, 2022). "IL-4+ cells in CD4+ T cells from DSS-induced colitis mice were significantly reduced compared to controls (23.96 ± 9.40% vs. 43.38 ± 2.55%, p < 0.01)." (PMID 35741032, 2022). "Albeit IFNγ expression was increased in CD69−CD103− and CD69+CD103+ CD4+ T-cell subsets during DSS-induced colitis, only small percentages of CD69−CD103− CD4+ T cells and CD69+CD103+ CD4+ TRM cells expressed IFNγ." (PMID 35844584, 2022). "In line with this, we found a greater expansion of proliferating CD4+ T cells in patients who developed colitis." (PMID 36173679, 2022). "Here, we report that TAGAP-deficient mice are susceptible to DSS-induced colitis, and this is due to significantly increased abundance of IL-17A-and IFN-γ-producing colitogenic CD4+ T cells in the gut." (PMID 36704549, 2022). "Studies using this CD4+CD45RBhigh adoptive transfer model also demonstrated the role of gut microbiota in shaping intestinal tolerance since CD4+CD45RBhigh T cells isolated from germ-free mice were unable to induce colitis in hosts." (PMID 36389662, 2022). "Profoundly, rutin inhibited the STAT4-IFN-γ pathway in splenic CD4+ cells of mice with CD4+CD62L+T cells transfer colitis." (PMID 35805952, 2022). "In contrast, cotransfer of CD4+YFP+Foxp3YFP-Cre Tregs or SRC2fl/fl/Foxp3YFP-Cre Tregs with naive CD4+ T cells rescued these severe colitis phenotypes in Rag1−/− mice." (PMID 35704583, 2022). "Transferring IBD microbiota induces more severe colitis in IL-10−/− mice and enhances naïve CD4+ T cell-induced colitis severity in Rag1−/− mice." (PMID 36076980, 2022). "Loss-of-function studies have suggested that IL-17+ and/or IL-17+IFN-γ+ CD4+ T cells are the major inducers of adaptive immune-driven colitis in a mouse model." (PMID 35468944, 2022). "As such, Arl4d−/− CD4 T cells induced significantly less colonic inflammation and lymphocytic infiltration in a model of transfer colitis." (PMID 36078047, 2022). "Transfer of CD4+CD25+ T cells has also been shown to cure colitis in a SCID mouse CD4+CD25- T cell transfer model with concomitant infection with Leishmania major." (PMID 36466912, 2022). "Together, these data suggest that in the humanized TNBS-treated mice, human CD4+ T cells mediate disease pathology, and more importantly, these mice enable the testing of human therapeutics targeting CD4+ T cells to treat colitis." (PMID 34571853, 2021).
colitis (continued). "During functional in vivo experiments, in comparison to conventional Tr1 cells that originate from naïve CD4+ T cells, both cells exhibit the same capacity to regulate colitis development." (PMID 33937944, 2021). "Administration of indole-3-pyruvic acid (I3Py) to mice with CD4+ T cell-induced colitis led to an increase in the amount of IL-10-producing T cells, while the number of Th1 cells in the mucosa was decreased, resulting in a reduction in colitis symptoms." (PMID 34073220, 2021). "A previous study demonstrating HDAC-i (ITF2357) mediated reduced IL-6 receptor expression on naïve CD4+T cells that leads to polarization of Th17 cells to Treg cells in experimental colitis is a likely mechanism of autoAb reduction." (PMID 35222229, 2021). "Rag1-deficient (−/−) mice were injected with 5 × 105 naïve T cells (CD3+CD4+CD45RBHi) to induce colitis." (PMID 34572293, 2021). "In the CD4 + CD45RO+hi transfer colitis model, authors investigated the effects of antagomiR-142-5p (5 mg/kg) treatment (starting at 5% weight loss for 5 days) by profiling the gene expression in the colons of these mice." (PMID 34571853, 2021). "For example, in an adoptive transfer model of colitis, transferring CD4+CD25- T cells from RORγt-/- mice to RAG-1-/- immunodeficient mice is unable to induce colitis, while treatment with IL-17A can restore colitis after the transfer of RORγt-/- T cells." (PMID 33754076, 2021). "Rag1-/- mice that received Themis-/- CD4+ Foxp3- T cells were resistant to developing colitis compared to the Rag1-/- mice that received Themis+/+ CD4+ Foxp3- T cells, as measured by increased body weight." (PMID 33177694, 2021). "Treg cells are considered to be an important subset of CD4+ lymphocytes that play a protective role in DSS-induced colitis in mice." (PMID 34804049, 2021). "The constitutive expression of TRPA1 mRNA and protein in mouse and human primary CD4+ T cells controls CD4+ T cell activation and pro-inflammatory responses in models of colitis." (PMID 34041030, 2021). "Based on the presented in vivo and in vitro studies, D3 signaling in CD4+ T balanced effector lineages and favored the inflammatory potential of CD4+ T-cells during chronic experimental colitis." (PMID 34884737, 2021). "Soluble fibers have been shown to up-regulate the ZO-1 and occludin expressions in the wild-type and the occludin in the CD4+CD62L+T cell transfer model of colitis mice." (PMID 35223407, 2021). "The CD4-dnTGFbRII mouse strain used in this study has a T cell-targeted inactivation of TGF-β that leads to spontaneous colitis with a massive infiltration of lymphocytes and activation of T cells in the intestine and other organs." (PMID 33717186, 2021). "For example, a study using a T cell transfer colitis model demonstrated that CD4(+) T helper cells strongly contributed to the pathogenesis of IBD." (PMID 34456974, 2021). "The administration of CLA protects against dextran sodium sulfate (DSS)-induced colitis as well as CD4+CD45RBhi T cell-induced colitis through a PPAR-γ-dependent mechanism." (PMID 33430497, 2021). "We observed the dynamic changes in CD4+ effector T cells involved in the pathological process of DSS-induced colitis in the mouse colon." (PMID 34336843, 2021). "Recently, we demonstrated that LD IL-2 was protective against experimental colitis in immune humanized mice in which human CD4+ T cells were restricted to human leukocyte antigen (HLA)." (PMID 33717161, 2021). "Deletion of GαS in CD4+ T cells results in reduced generation of cAMP, decreased calcium flux, and the inability to induce colitis in an adoptive transfer model, underscoring the importance of this pathway in CD4+ T cell–driven inflammation." (PMID 33651234, 2021). "IL-6 production by lamina propria macrophages and CD4+ T cells was increased in experimental colitis and in patients with IBD." (PMID 33633749, 2021).
colitis (continued). "In the CD4+CD45RBhigh T-cell-transferred colitis model, IFN-γ-producing effector T (Teff) cells including conventional T helper 1 (Th1) cells and IFN-γ/IL-17-co-expressing T helper 17 (IFN-γ-producing Th17) cells are responsible for the pathogenesis." (PMID 34475823, 2021). "It has been reported that CD4+ CD25+ T cells inhibit the development of colitis induced by both Th1 and Th2 cells in a mouse model." (PMID 34456974, 2021). "Strikingly, the exacerbated intestinal inflammatory response observed in Lgals1−/− mice was alleviated by adoptive transfer of wild type Foxp3+CD4+ regulatory T cells at induction of colitis." (PMID 34262567, 2021). "Our prior work demonstrated critical cell-autonomous contributions of Bcl-3 in maintaining pathogenic Th1-like, IFN-γ producing CD4+ T cells in the context of EAE and colitis." (PMID 33508001, 2021). "Classically, colitis induced using the adoptive transfer of CD4+CD45RBhigh T cells into Rag 1, 2 knockout mice that lack T and B cells has been considered to be Th1 -mediated." (PMID 34136502, 2021). "First, we utilized a classic model of colitis induced by adoptive transfer of normal CD4+CD25−45RBhi T cells into Rag 1−/− recipient mice, which also induced ovarian insufficiency mimicking human POI." (PMID 34185428, 2021). "In this study, we observed that CD4+ T cells were significantly recruited to the isolated lymphoid follicles (ILFs) in the colon of mice with DSS-induced colitis, indicating CD4+ effector T cells are involved in the inflammatory process of colitis." (PMID 34336843, 2021). "During acute colitis, the percentage of CD4+ T-cells in the mesenteric lymph nodes of resveratrol-treated mice have remained at normal levels while CD4+ T-cell numbers in the lamina propria decreased." (PMID 34944544, 2021). "To explore this in vivo, we used a mouse model of inflammatory bowel disease where transfer of naive CD4+ T cells into RAG1-deficient mice, which lack their own lymphocytes, drives colitis." (PMID 34216540, 2021). "Transfer of naive CD4+ T cells alone efficiently induced colitis in recipient mice, limiting survival." (PMID 34216540, 2021). "In a mouse colitis model, transferring naïve CD4+ T cells into mice with DCs with a specific deletion of SIRT1 aggravated colonic inflammation and promoted weight loss." (PMID 34887866, 2021). "Significantly, genetically or pharmacologically activating Hh signalling has been reported to ameliorate colitis by inducing the expression of IL-10 in Hh-responsive stromal cells, which subsequently increases the amount of CD4+Foxp3+ regulatory T cells." (PMID 34702800, 2021). "In this T cell-mediated model of colitis, the transfer of naïve CD4+ T cells into lymphopaenic recipients (Rag1−/−) results in colitis that is driven by the activation and expansion of the transferred T cells." (PMID 33524014, 2021). "Transfer of CD4+CD45RBhi T cells from Trp73 cKO mice into Rag2−/− mice resulted in accelerated colitis development compared to mice that received WT CD4+CD45RBhi T cells from littermate controls." (PMID 32193462, 2020). "Flow cytometry results revealed that the percentages of CD4+ cells in the mesenteric lymph nodes (MLN) were lower in DSS colitis mice than in healthy controls." (PMID 31903161, 2020). "Colitis can be artificially induced by transferring naive CD45RBhigh CD4+ T cells into immunodeficient Rag1−/− mice, characterized by colon thickening, and ultimately weight loss." (PMID 32463116, 2020). "Previous study showed that the subepithelial layer was enriched with CD4+ T cells in colitis induced by CTLA-4 inhibitors." (PMID 33123120, 2020). "One possible reason is that in approximately 8 days of acute colitis model, CD4+ T cells gradually entered a resting stage." (PMID 32391010, 2020). "Reduced EdU incorporation in Btk−/− CD4+ T cells was also confirmed in mice with T-cell-mediated colitis." (PMID 31431692, 2020).
colitis (continued). "Colitis was induced after a further 2 wk by the transfer of naive (CD45RBHI CD25−) CD4+ T cells, and colitis was monitored by changes in body mass." (PMID 32817490, 2020). "CD4+Foxp3+Treg cells play a major role in immune homeostasis, and their expression is decreased in colitis mice." (PMID 32581849, 2020). "Oral inoculation of Clostridia strains attenuated the colitis of adult mice induced chemically or by the transfer of CD4+CD45RBhi T cells, providing another potential for treatment for IBD by rectifying bacterial dysbiosis." (PMID 32983168, 2020). "It has been reported that overexpression of c-Maf in naïve CD4+ T cells reduces Th1-mediated colitis compared with wild-type controls, but memory T cells with enhanced c-Maf expression exacerbate the development of colitis." (PMID 32369982, 2020). "Our colitis model with the CD4-Cre+/TgMettl14FL/FL conditional knockout mice has 100% penetrance with all mice developing early signs of colitis by week 6, and the colitis phenotype becomes progressively more severe over time." (PMID 32634481, 2020). "Based on our results, we concluded that CD4+ T helper- (Th-) type 2 cells producing IL-13 and B cells producing IgE were responsible for mediating colitis in mice." (PMID 32410852, 2020). "Current evidence from animal models of colitis and human studies reveal that both innate lymphoid cells (ILCs) and CD4+ T helper (Th) cells are major mediators for the pathogenesis of chronic intestinal inflammation in IBD." (PMID 32369982, 2020). "We examined the mechanism underlying the therapeutic effect of the anti-CD81 antibody and found that CD4+ T cells were decreased in colons of mice with colitis treated with the anti-CD81 antibody." (PMID 32332834, 2020). "The T. spiralis secreted serine protease alleviated the severity of TNBS-induced colitis by balancing the CD4+ T cell immune response." (PMID 33117347, 2020). "We found that treating the CD4-Cre+/TgMettl14FL/FL conditional knockout mice with ciprofloxacin + metronidazole prevented the development of colitis phenotype as assessed by normal colonic weight-to-length ratio and eliminated inflammatory cell infiltration." (PMID 32634481, 2020). "By using Treg cells isolated from Cd4creTgfb1fl/fl mice, it has also been demonstrated that TGF-β1 producing capacity is required for Treg cells to inhibit the induction of Th1 cells from naïve CD4+ T cells in an animal model of T cell-mediated colitis." (PMID 32471185, 2020). "A key role for NCOR1 in regulating Th effector functions was further identified in vivo in an adoptive CD4+ T cell transfer model of colitis." (PMID 32318068, 2020). "CD4+CD45RBhigh T cells were injected into SCID mice to induce immune memory dysfunction in colitis mice." (PMID 33597887, 2020). "In this study, we focused on the interaction of commensals with DCs and the resulting CD4+ T cell response in vitro and in vivo in an autoimmune-driven mouse model of colitis." (PMID 33542719, 2020). "This is consistent with another observation that GSK3β deletion in CD4+ T cells improves the survival of T cells and ameliorates colitis." (PMID 32670290, 2020). "In the colitis prevention model, B6/Rag1−/− mice were adoptively transferred i.p. with 1 × 106 WT CD4+CD25− Tconv together with 5 × 105 CD4+CD25+ Treg from either WT or HDAC10−/− donors simultaneously." (PMID 31949209, 2020). "They demonstrated that after treatment with the inhibitor PRN 694 in a transfer colitis model, the mice showed a smaller proportion of CD4+ cells in the lamina propria (LP) as well as in the intestinal epithelium." (PMID 32808093, 2020). "A variety of genera can reduce the immune checkpoint inhibitor-induced colitis possibly by limiting the inflammation through expansion of CD4+/FoxP3+ T reg cells and/or production of anti-inflammatory cytokines." (PMID 32793150, 2020).
colitis (continued). "Employing the CD4+CD25− naïve T cell transfer model, we found that T cells fail to elicit colitis in IRF4-deficient compared to IRF4-proficient Rag1−/− mice." (PMID 33584655, 2020). "We also found that the colitis is dependent on the microbiome as we were able to suppress colitis development in the CD4-Cre+/TgMettl14FL/FL conditional knockout mice with antibiotic treatment." (PMID 32634481, 2020). "Our results also demonstrated that colonization with CD4+T cells was dramatically increased in DSS-induced colitis, and TS inhibited the recruitment of CD4+T cells." (PMID 33363184, 2020). "Both experimental murine colitis models and patient studies argue for a role of CD4+ T-cell derived IL-9 in IBD." (PMID 31906479, 2020). "Depletion of CD4+ T cells led to more severe colitis, and depletion of both CD4+ T cells and ILCs further aggravated the severity of colitis, indicating that both CD4+ T cells and ILCs are critical in protecting the intestines against C. rodentium infection." (PMID 32901017, 2020). "For instance, IFN-γ produced by CD4+ T cells plays a role in ameliorating the development of colitis by induction of major histocompatibility complex II (MHCII) expression in epithelium." (PMID 32453801, 2020). "To investigate the role of Tregs in controlling the CD4 T cell response, we employed a model of S. Tm colitis with an attenuated strain allowing identification of an S. Tm-specific T cell clonotype." (PMID 32457450, 2020). "Due to reduced numbers of peripheral T cells in NCOR1 cKOCd4 mice, we employed an adoptive CD4+ T cell transfer model of colitis to start with comparable numbers of WT and NCOR1 cKOCd4 CD4+ T cells." (PMID 32318068, 2020). "Accordingly, miR-126-deficient mice have reduced TREG cells and increased activated peripheral CD4+ T cells, and develop severe colitis when challenged with DSS." (PMID 32155783, 2020). "Despite the fact that they demonstrated that the CD4+ cells only represent a small fraction of the total lymphocyte population, they were able to image the CD4+ cells in the gut specifically in mice with colitis using SPECT/CT87." (PMID 31903161, 2020). "Excessive colitogenic CD4+ central memory T cells (CD4+ TCM) are preferentially retained in the bone marrow of mice with colitis, and they circulate between the bone marrow and the lamina propria." (PMID 33597887, 2020). "A previous study showed that CD4+ T cells in IL-10-/- mice produced similar IFNγ levels compared to CD4+ T cells in IL-23-/-IL-10-/- mice in spontaneous model of colitis, indicating normal Th1 response in IL-23- and IL-10-deficient environment." (PMID 33488580, 2020). "In this model, transfer of naive CD4+CD45RBhi T cells from WT mice into Rag2−/− mice results in frank colitis development 8–10 weeks after transfer in our animal facilities." (PMID 32193462, 2020). "We were able to confirm the capacity of Lr 5454 in inducing Tregs in in vitro DC/CD4 T cell co-culture, providing a possible explanation for its protective effect against colitis." (PMID 32210304, 2020). "In the same way, the administration of exosomes secreted by dendritic cells expressing TGF-β1 alleviates DSS-induced colitis, which is mediated by Th17 responses, by inducing CD4+ Foxp3+ Treg cell activation." (PMID 32365813, 2020). "For example, expression of human MHC class I and II transgenes in NSG mice has facilitated the study of CD8+ and CD4+ T cell responses in graft-versus-leukemia immunity and colitis, respectively, in Hu-PBMC-NSG mice." (PMID 33123018, 2020). "It has been studied the role of CD4+CD25-GITR+ and CD4+CD25+GITR+ T cells in a well-described CD4+CD45RBhi T cell SCID-transferred colitis model." (PMID 33163004, 2020). "Next, to investigate the physiological effects of Nfil3-overexpressing Treg cells, we injected Treg cells intraperitoneally into Rag1 knockout (KO) mice, along with naive CD4 T cells, to induce colitis." (PMID 31311918, 2019).